MMGT1 (membrane magnesium transporter 1)
Description:
Part of the endoplasmic reticulum membrane protein complex (EMC) that enables the energy-independent insertion into endoplasmic reticulum membranes of newly synthesized membrane proteins. Preferentially accommodates proteins with transmembrane domains that are weakly hydrophobic or contain destabilizing features such as charged and aromatic residues. Involved in the cotranslational insertion of multi-pass membrane proteins in which stop-transfer membrane-anchor sequences become ER membrane spanning helices. It is also required for the post-translational insertion of tail-anchored/TA proteins in endoplasmic reticulum membranes. By mediating the proper cotranslational insertion of N-terminal transmembrane domains in an N-exo topology, with translocated N-terminus in the lumen of the ER, controls the topology of multi-pass membrane proteins like the G protein-coupled receptors. By regulating the insertion of various proteins in membranes, it is indirectly involved in many cellular processes (By similarity). May be involved in Mg(2+) transport (By similarity).
Synonyms: EMC5; TMEM32
Tractability: Small molecule: a structure with a bound ligand is known. Antibody: UniProt predicts a signal peptide or a membrane-spanning region; its Gene Ontology location is reachable by antibodies, with medium confidence. PROTAC: ubiquitination databases record sites on it; its protein half-life has been measured.
Gene: Protein-coding gene on chromosome X (135,960,588 to 135,974,029, reverse strand). Ensembl gene ENSG00000169446.
Subcellular location: Endoplasmic reticulum membrane; Golgi apparatus membrane; Early endosome membrane
Pathways (Reactome):
Transport of small molecules: Miscellaneous transport and binding events
Gene Ontology:
Molecular function: membrane insertase activity; protein binding; magnesium ion transmembrane transporter activity; transmembrane transporter activity; cobalt ion transmembrane transporter activity; ferrous iron transmembrane transporter activity
Biological process: protein insertion into ER membrane by stop-transfer membrane-anchor sequence; tail-anchored membrane protein insertion into ER membrane; magnesium ion transport; cobalt ion transport; iron ion transmembrane transport; magnesium ion transmembrane transport; transmembrane transport
Cellular component: EMC complex; endoplasmic reticulum membrane; membrane; early endosome; early endosome membrane; Golgi apparatus; Golgi membrane; plasma membrane; cytoplasm; endomembrane system
Homologues: Orthologues: chimpanzee MMGT1 (100% identical), macaque MMGT1 (99% identical), pig MMGT1 (98% identical), mouse Mmgt1 (95% identical), rat Mmgt1 (95% identical), zebrafish mmgt1 (78% identical), tropical clawed frog mmgt1 (67% identical). Paralogues in human: NDUFAF6 (26% identical).
Diseases named in the same sentence as MMGT1 in open-access papers:
MMGT1 is named in the same sentence as 5 diseases in open-access papers, as found by Europe PMC text mining. Sharing a sentence is not in itself a finding about the gene and the disease. The quoted sentences say what the papers report.
tumor (2 papers, 2020 to 2022). "In a subsample of patients whose tumours were profiled for RNA (n = 96), feature S(1,−1)SumAverg was significantly associated with the expression of gene MOV10L1, LRP1B, ZFY, PITX2, TRAPPC12, MMGT1 and PPP2R2C (all P < 0.05)." (PMID 36050449, 2022).
MMGT1 also shares sentences with these, for which no sentence is quoted: infection (2 papers); Candida infections (1); retinal degeneration (1); virus infection (1).